IL1B (interleukin 1 beta)
Diseases named in the same sentence as IL1B in open-access papers (continued):
Sharing a sentence is not in itself a finding about the gene and the disease.
tumor (continued). "First, activation of TAMs releases IL‐1α and IL‐1β to act on tumour cells, activating the intracellular NF‐κB pathway, which next exerts a pro‐coagulant effect by affecting NLRP3 inflammatory vesicles." (PMID 38652105, 2024). "In some studies, the outcome of chemotherapy has indeed been improved by the combination of cytotoxic drugs and IL-1β/IL-1R inhibitors, such as anakinra, limiting the pro-tumor effects of IL-1β." (PMID 38334625, 2024). "This is pertinent, as ccRCC cells generally exhibit low levels of CXCL7, yet its expression becomes notably elevated within the tumour milieu due to heightened IL‐1β levels." (PMID 39011666, 2024). "Our study found that the expression of IL-1β was significantly higher in ESCC tumor tissues than in paracancerous tissues, which aligns with the results obtained from the TIMER, GEPIA, and UALCAN database." (PMID 38762529, 2024). "HC reduces histamine-induced mast cell infiltration and downregulates IL-1β to alleviate skin itching." (PMID 39338343, 2024). "Our results define the role of IL-1β specifically in the DC population within the tumor microenvironment, where it is known to regulate their inflammatory activity through IL-12 production." (PMID 39576827, 2024). "IDO1 expression can be either triggered as a counter regulatory response to cytokines like IL-1β and IL-6 released from tumor-infiltrating immune cells or maintained through tumor-intrinsic oncogenic signaling." (PMID 38218942, 2024). "Research has indicated that tumor cells secrete cytokines, such as granulocyte colony-stimulating factor (G-CSF), interleukin-1β (IL-1β), interleukin-6 (IL-6), and tumor necrosis factor (TNF), which are believed to extend the lifespan of neutrophils." (PMID 39143953, 2024). "On the other hand, NLRP3 inflammasome activation can lead to excessive production of inflammatory cytokines such as IL-1β and IL-18, significantly affecting the tumor microenvironment and potentially promoting HCC growth." (PMID 39544286, 2024). "IL-1B+ macrophages were significantly enriched in the terms cytoplasmic translation, ribosome, ATP metabolic process and cell proliferation, suggesting that IL-1B+ macrophages are involved in the regulation of tumor growth." (PMID 39702278, 2024). "MMPs (especially MMP9) stimulate tumor cell proliferation and the production of VEGF and subsequent angiogenesis, while IL-6, IL-1β, and TNF-α, among pro-inflammatory cytokines, support chronic inflammation preceding or associated with tumor." (PMID 38612841, 2024). "On the other hand, the inhibition of NLRP3 inflammasome using MCC950 reduced LPS, ATP, PTX-mediated caspase-1 and IL-1β release, both in normal cells (p < 0.01 and p < 0.001, respectively) and tumor cells (p < 0.001 and p < 0.0001, respectively)." (PMID 39433537, 2024). "In this study, we identified a different regulatory way by which SPP1 + Macs released the cytokines TNF-α and IL-1β to promote tumor progression." (PMID 39726047, 2024). "Thus, another goal of this study was to determine whether HIFU treatment causes an influx of immune cells into the tumor area and the expression of pro-inflammatory cytokines: interleukin-1α (IL-1α), interleukin-1β (IL-1β), interferon γ (IFN-γ), and tumor necrosis factor α (TNF-α)." (PMID 39199617, 2024). "Prior investigation has found that IL-1β can positively regulate the self-renewal of cancer stem cells, thereby expediting tumor growth and invasion." (PMID 38001342, 2024). "During pyroptosis, tumor cells secrete inflammatory cytokines that consist of IL-1β and IL-18, which attract macrophages and CTLs and promote tumor cell elimination." (PMID 39200381, 2024). "While empty vector-electroporated tumors grew rapidly, the IL-1β-enriched pyroptosis efficiently aborted tumor growth and led to tumor elimination and long-lasting survival in 80% of mice." (PMID 39737979, 2024). "The TAMs release IL-6, and other cytokines (e.g., IL-1β) that promote tumor progression [Buonfiglio and Hambardzumyan, 2021]." (PMID 39512605, 2024).
tumor (continued). "The presence of prostaglandin E2 (PGE2) and tumor necrosis factor (TNF) within the TME led to the conversion of tumor-infiltrating monocytes in interleukin-1β (IL-1β)-expressing TAMs." (PMID 38817612, 2024). "In a cohort of OS patients, the levels of IL-1β, IL-1R, and IL-1RAP expression in tumor samples were directly correlated with the presence of metastases and inversely correlated with the degree of tumor necrosis after neoadjuvant chemotherapy." (PMID 38334625, 2024). "The spatial proximity of IL-1β+ TAMs and cancer cells drive the acquisition of inflammatory and pathogenic properties of a subset of PDAC cells expressing an IL-1β response signature during the early stages of tumor development." (PMID 38817612, 2024). "Probiotic strains and bacterial CFSs that promote generalized mucosal immune responses via proinflammatory cytokine production (e.g., TNF-α, IL-1β and IL-6) were found to fortify the host defense system and provide anti-pathogen and anti-tumor effects." (PMID 39534506, 2024). "TAMs-derived IL-1β stimulates GBM tumor cells and induces the expression of IL-1β itself and CCL2, which actively recruits TAMs in the tumor site." (PMID 38397187, 2024). "It is critical to understand how cytokines such as IL-1β and IL-6 regulate the transcription of inflammatory genes in the tumor microenvironment and how these cytokines interact with immune cells in that microenvironment." (PMID 39526199, 2024). "The tumor-associated macrophages (TAM) exhibit reduced expression of the M1 genes Tnfa, Ccl3, and Il1b, but elevated levels of the M2 markers Ym1, Fizz1, Il1ra, Mgl1, and Mgl2 following the respective stimulation for M1 or M2 phenotype polarization." (PMID 38629061, 2024). "Increased evidence indicates that bone-derived transforming growth factor-beta (TGF-β1) and IL-1B can reactivate dormant disseminated tumour cells (DTCs) stimulating metastatic outgrowth in the bone." (PMID 38800348, 2024). "Regarding the protumor potential, it has been discovered that both IL-1α and IL-1β help with tumor angiogenesis and invasiveness as PCa develops." (PMID 38745115, 2024). "Circulating tumour cells (CTCs) and interleukin-1β (IL-1β), interleukin-6 (IL-6), interleukin-8 (IL-8), and interleukin-10 (IL-10) were measured in a pilot group of 40 patients at baseline and before cycle two (C2) and cycle three (C3)." (PMID 38398148, 2024). "IL-1B is involved in the growth of the primary tumours, regulation of inflammation within the tumour microenvironment, promotion of epithelial to mesenchymal transition (EMT), migration and invasion." (PMID 38800348, 2024). "Conversely, IL‐6 and IL‐1β protein levels were elevated in the tumour tissues of GV493‐RNAi cell xenotransplanted nude mice models." (PMID 39495702, 2024). "We confirmed that both IL-1α and IL-1β were highly upregulated at the protein level in the tumor-bearing lungs of old mice by ELISA." (PMID 39236155, 2024). "SAADKO tumor-bearing mice displayed lower concentrations of IL-1β (p = 0.030), IL-6 (p = 0.003), and IL-10 (p = 0.014) compared to WT tumor-bearing mice." (PMID 39336082, 2024). "Our pseudotime analysis suggests a developmental trajectory of neutrophils that progresses from the healthy subtype to the tumor-specific population and finally a metastasis-specific population; a lineage that is largely driven by IL1β/CXCL8/CXCR2 axis." (PMID 38358352, 2024). "IL1A, exhibiting similarities to IL1B, displayed a tenfold increase in 44% of the tumor samples, though its average normalized count in tumors was notably lower." (PMID 38979413, 2024). "During the initial stages of the tumor, resident immune cells within the tissue microenvironment secrete the pro-inflammatory cytokine IL-1β, serving as a primary activator of NF-κB to initiate crosstalk between CAFs and tumor cells." (PMID 39680287, 2024).
tumor (continued). "While IL-1β produced by MDSCs contributes to immune suppression and tumor growth, IL-1β from dendritic cells (DCs) can stimulate T-cell immunity, enhancing anti-tumor responses." (PMID 39766056, 2024). "Extracellular secretion of cytokines, such as IL1β or TNFα, and lymphokines is noticeable in the tumor stroma, as well as the presence of growth factor VEGF-A, which is linked to tumor blood vessel formation." (PMID 39625899, 2024). "PGE2, a significant inflammatory mediator, has been shown to promote the accumulation of IL-1β + TAMs and monocytes, enhancing tumor growth." (PMID 39068459, 2024). "TNBC cells are characterized by Notch-dependant IL1β expression and Notch-independent expression of caspase-18,9, both prerequisites for IL1β maturation and the recruitment of pro-tumoral TAMs to the tumor microenvironment." (PMID 39353903, 2024). "Our results indicate that the IL‐1β rs16944 A/A genotype is involved in number of circulating tumor cells, microscopic portal vein invasion, and prognosis in HCC." (PMID 38798075, 2024). "Macrophages are tumor-promoting cells acting by secreting cytokines, such as IL-6, IL-1β, and TNF-α." (PMID 39064019, 2024). "IL-1β also recruits proangiogenic macrophages, which explains why using an IL-1β antagonist can reduce tumor inflammation, angiogenesis and growth." (PMID 39195299, 2024). "Tumor growth is driven directly by M2-like macrophages through the release of IL-1β, IL-6, IL-10, CCL18 and CCL20, as well as indirectly through the suppression of cytotoxic cell populations, including CD8+ T cells and NK cells." (PMID 38957393, 2024). "Mice lacking ASC and caspase-1 showed an increased tumor burden related to attenuated levels of IL-1β and IL-18 in the site of the tumor." (PMID 39684769, 2024). "Further research is needed to fully elucidate the interplay between different cell populations in the tumor microenvironment and their collective impact on IL-1β signaling and cancer progression." (PMID 39801513, 2024). "This process releases immunostimulatory molecules like IL-1β, enhancing T cell infiltration and activity within the tumor microenvironment." (PMID 39439792, 2024). "IL-1β derived from tumor cells can activate pancreatic stellate cells (PSCs), which in turn leads to mesenchymal fibrosis, inhibiting T cell infiltration." (PMID 39034996, 2024). "IL-1β is known to drive bone metastasis by promoting tumor cell migration and invasion, as well as by facilitating the interaction between cancer cells and bone cells, which supports metastatic outgrowth." (PMID 39125732, 2024). "IL-1β induces tumor angiogenesis through activation of the vascular endothelial growth factor pathway, increases immunosuppressive cells, and accelerates tumor invasion via secretion of GM-CSF and IL-6." (PMID 38580797, 2024). "The just‐mentioned immunosuppressive mechanism in the tumor microenvironment is supported by an autoinflammatory loop regulated via the IL‐1β/IL‐6/signal transducer and activator of transcription 3 (STAT3) axis." (PMID 38775220, 2024). "Our study demonstrates that TIBs induce an inflammatory response leading to the secretion of IL-1β by tumor cells." (PMID 39801513, 2024). "IL1B was highly expressed in adrenocortical and medullary tumor samples obtained from the ACME HS and nuclei datasets, while IL6 was highly expressed in all tissues compared with the PitNET datasets obtained by the enzymatic digestion method." (PMID 39839668, 2024). "IL1B+ TAMs expressing inflammatory factors and chemokines promote anti-tumor immunity not only by recruiting inflammatory cells and activate inflammatory responses but also by enhancing adaptive immune responses through its interaction with T cells." (PMID 39232806, 2024). "To further confirm IL-1β signaling, we tested the ability of B cells to activate IL-1β-dependent NFκB signaling in tumor cells by assessing phosphorylation of serine 536 of the p65 (RELA) subunit." (PMID 39801513, 2024).
tumor (continued). "Cytokines, including IL1B and other IL-1 family members, are associated with various aspects of CRC progression, promoting tumor immune evasion, cell survival, and proliferation." (PMID 38979413, 2024). "IL-1β and IL-6 are highly expressed within the tumor microenvironment (TME) and play well-established roles in PDAC development and progression." (PMID 39260693, 2024). "IL-6, a well-established cytokine induced by IL-1β in intestinal epithelial cells (IECs), has been shown to promote tumor progression in CAC through the activation of the oncogene STAT3 in addition to IL-11." (PMID 38607004, 2024). "To understand the role of IL-1β in tumor progression, we transfected KYSE150 and EC109 with siRNA and lentivirus to construct cellular models for knockdown and overexpression of IL-1β." (PMID 38762529, 2024). "Here we report that, while inflammasomes have traditionally been described in immune cells, activated caspase-1 is expressed in TNBC cells allowing IL1β maturation, macrophage recruitment, and tumor progression." (PMID 39353903, 2024). "M1 can enhance the expression of MHC-II+, TNF-a, IL-1β, and IL-6, enhance the production of reactive oxygen species and NO, and have certain tumor damage activity." (PMID 39351151, 2024). "In vivo studies have also shown that blockade of IL-1β increased the numbers of tumor-infiltrating lymphocytes and CD8+ T-cell responses." (PMID 38730319, 2024). "The increase in IL‐1β was also evident in the heart indicating a possible conserved response of striated muscle to the tumor." (PMID 39294861, 2024). "IL1B+ monocytes highly expressed the proinflammatory factors and had tumor-promoting function by regulation of the epithelial–mesenchymal transformation pathway." (PMID 38672120, 2024). "Existing literature analysis revealed a simultaneous upregulation in TNF-α, IL-6, and IL-1β expression in tumor-bearing mice's hippocampus at that same time point, with mRNA levels aligning with observed plasma cytokine increases." (PMID 39286150, 2024). "Many studies have focused on the role of cytokines and cytokine receptors as potential targets for tumor intervention, including the inhibition of the tumor-promoting functions of IL-1β, IL-6, and TNF." (PMID 38317842, 2024). "Among different cancer types (ER+, HER2+ and TNBC) and other tumor-associated cells, we almost exclusively observed CLEC10A expression in the myeloid cell cluster, preferentially in cDC2 and IL1B+ monocytes of which more than 40% of cells expressed CD301." (PMID 38206856, 2024). "Recent research indicates that tumor cells can directly produce IL1β, rendering treatments ineffective." (PMID 39766172, 2024). "IL-1β was shown to upregulate OPG expression in MAPK-dependent pathways and enhance its secretion by tumor cells, associated with macrophage infiltration." (PMID 39201656, 2024). "IL-1β can reduce PD-L1 levels in tumour cells and suppress the infiltration of Mφs in vivo, increasing the antitumour efficacy." (PMID 39735605, 2024). "In our integrated mouse dataset, Il1b was upregulated in the lineages ending with the tumor clusters." (PMID 38358352, 2024). "Further co-culture studies using three TNBC cell lines (SUM159, MDA-MB-231, and non-invasive MCF12A) confirmed significant increases in IL-1β gene expression in tumor cells when co-cultured with the EBV-transformed B cells." (PMID 39801513, 2024). "It was also found that the combined function of IFN-γ, TNF-α, and IL-1β will stimulate CCL22 secretion by tumor cells." (PMID 39003350, 2024). "Treatment of tumor bearing mice with WFA showed a significant reduction in IL-1β expression levels (p < 0.001)." (PMID 39394174, 2024). "On the other hand, M2 macrophages express high levels of VEGF, IL-10, IL-1β, and matrix metalloproteinases (MMPs), which contribute to chemoresistance, tumor angiogenesis and metastasis." (PMID 39003350, 2024).
tumor (continued). "In tandem, inflammasome activation and the involvement of the GSDMD protein reshape the tumor microenvironment by influencing the secretion and release of the ultimate products of pyroptosis, namely IL-1β and IL-18." (PMID 38001342, 2024). "A recombinant form of IL-1Ra is commercially available and is known as anakinra, commonly used to treat arthritis and recently repurposed also for anti-cancer therapies against bone metastases to antagonize the many pro-tumor activities of IL-1β." (PMID 38334625, 2024). "NLRP3 inflammasome activation, such as IL-1β and IL-18 production, promotes immune cell infiltration in the tumor microenvironment and enhances chemotherapy-induced anti-tumor immunity." (PMID 38575922, 2024). "Such analysis demonstrated an increase in NLRP3 and IL1B gene expression in tumor-infiltrating myeloid cells, which was consistent with transcriptomic results from in vitro experiments." (PMID 38576612, 2024). "Following pFUS, there was a 75% concordance for anti-tumor cytokines and inflammatory markers (including TNFα, IL-1a, IL-1b, IL-17, IL-6, and VCAM-1), indicating a TME shift toward a hot TME." (PMID 38543305, 2024). "MSCs can be stimulated within the tumour niche by pro-inflammatory cytokines such as TNF-α, IFN-γ or IL-1β, which are produced by both macrophages and tumour cells." (PMID 39120301, 2024). "Strikingly, still, both IL-1α and IL-1β production by lung MPs were significantly increased in tumor-bearing lungs of old mice than in young mice, suggesting that hematopoietic aging enhances their production." (PMID 39236155, 2024). "Proinflammatory interleukins, such as interleukin-1β (IL-1β) and interleukin-18 (IL-18), play a significant role in cancer progression by modulating the tumor microenvironment and influencing various stages of tumor development." (PMID 39125732, 2024). "Inflammatory vesicle‐dependent IL‐1β and IL‐18 exert anti‐tumour effects or pro‐tumour effects mainly depending on the TME." (PMID 38652105, 2024). "One of the major cytokines involved in this inflammation is IL-1β, which promotes tumor growth and invasiveness through the stimulation of IL-6, TGFβ, and TNFα." (PMID 39394174, 2024). "Quercetin can inhibit the formation of immune mediators that induce inflammation, like IL-1β and IL-8, which contribute to a tumor-promoting inflammatory environment." (PMID 39683540, 2024). "TANs, in turn, release IL-1β to activate PSCs, forming a positive feedback loop that promotes tumor growth." (PMID 38590651, 2024). "Inflammatory cytokines, such as IL-1β and IL-18, which are released during pyroptosis, are also key players in tissue inflammation, tumor immunity, and cancer progression." (PMID 38649701, 2024). "These transcription factors lead to the secretion of pro-inflammatory cytokines, including TNF-α, IL-1β, and IL-6, which further promote tumor growth." (PMID 39267826, 2024). "Notable, IL-15, IL-18, IL-1β, and TNFα in the host serum, potentially derived from the tumor microenvironment through various pathways, promoted sustained angiogenesis involving endothelial cells." (PMID 39451257, 2024). "Further analyses identified tumor monocytes as the principal producers of both IL-1β and IL-1α at the RNA and protein levels." (PMID 39030280, 2024). "Further, IL-1β has been shown to enhance the recruitment of immunosuppressive myeloid cells to the tumor and to promote tumor angiogenesis." (PMID 39224600, 2024). "In summary, these data indicate that IL-1β and M2 TAMs can support OS tumor growth, malignancy, immune escape, and drug resistance by activating multiple cell-intrinsic and -extrinsic mechanisms." (PMID 38334625, 2024). "COX-2 expression that is also induced by IL-1β, inhibits antigen presenting cells from maturation and activation at the tumor microenvironment." (PMID 38553531, 2024). "IL-1β secreted by tumor cells promotes the infiltration of both M2-like TAMs and TANs into the PDAC immune microenvironment." (PMID 40458305, 2024).